NOTCH1 (notch receptor 1)
Diseases named in the same sentence as NOTCH1 in open-access papers (continued):
Sharing a sentence is not in itself a finding about the gene and the disease.
T-cell acute lymphoblastic leukemia (continued). "Dysregulation of the NOTCH1 pathway is known in a variety of solid cancers and hematological malignancies, especially in T-cell acute lymphoblastic leukemia (T-ALL), where the determination of NOTCH1 is already recommended for clinical routine and characterization." (PMID 37833915, 2023). "In patients with T-cell acute lymphoblastic leukemia (T-ALL), HIF-1α is overexpressed, and HIF-1α can promote the activation of Notch1 signaling, increase the expression of cyclin D1, CDK2, p21, MMP2, and MMP9 proteins, thereby leading to cell proliferation, invasion, and resistance." (PMID 35684364, 2022). "For example, VAV1 can unexpectedly play non-catalytic tumor suppressor functions in T-cell acute lymphoblastic leukemia (T-ALL) by controlling the levels of the active form of NOTCH1 (ICN1)." (PMID 34571765, 2021). "In the Notch1-induced T-cell acute lymphoblastic leukemia (T-ALL) mouse model, Notch1 increases Jmjd3 expression likely via NFkB, which in turn enhances the expression of Notch1 target genes in cooperation with Notch1, while Utx suppresses the T-ALL formation." (PMID 33633164, 2021). "In addition, in T-cell ALL, PRDM14 binds an intron of Notch1 gene and modifies the chromatin structure by inducing H3K4me3, allowing the access of the RAG recombinase complex." (PMID 32290321, 2020). "Similarly, in human T cell acute lymphoblastic leukemia (T-ALL), NOTCH MYC enhancer (N-Me) acts as a critical mediator of NOTCH1 induced MYC expression required for T cell development and T cell transformation." (PMID 31311566, 2019). "Likewise, in T cell acute lymphoblastic leukemia (T-ALL), repression of tumor suppressor miR-451 is essential for NOTCH1-induced oncogenesis by directly targeting c-Myc." (PMID 26164082, 2015). "Indeed, we and others have previously suggested that induction and maintenance of T-cell acute lymphoblastic leukemia (T-ALL), a devastating pediatric blood cancer, depends on the cross talk of three transcription factors, NOTCH1, MYC, and RELA (NF-κB)." (PMID 21356087, 2011). "In T-cell acute lymphoblastic leukemia (T-ALL), IGF2BP2 binds to the oncogene NOTCH1 via an m6A-dependent mechanism and contributes to leukemogenesis." (PMID 40332203, 2025). "Current models suggest that RUNX1 cooperates with other oncogenic factors (e.g., NOTCH1, TAL1) to drive the expression of proto-oncogenes in T cell acute lymphoblastic leukemia (T-ALL) but the molecular mechanisms controlled by RUNX1 and its cooperation with other factors remain unclear." (PMID 37213235, 2023). "Moellering and colleagues (2009) were the first to demonstrate that a hydrocarbon-stapled peptide derived from a dominant negative form MAML1 known as SAHM1 competitively bound Notch1-CSL transcriptional complex to repress Notch1 target gene expression in T-cell acute lymphoblastic leukemia (T-ALL)." (PMID 33003540, 2020). "Additionally, siRNA mediated knockdown of Tspan33 in HeLa cells reduced the γ-secretase dependent cleavage of a constitutively active, truncated form of Notch1 and that of T-cell acute lymphoblastic leukemia (T-ALL) Notch1 oncogenic mutants." (PMID 28066176, 2016). "Interestingly, expressing supra-physiological levels of Notch1 ICD, as determined by the elevated levels of Hey1 expression, did not generate a phenotype, which is in contrast to other situations of hyperactivated Notch signaling, for example in acute lymphoblastic T-cell leukemia." (PMID 29140246, 2017). "sel-10 was found as a negative modulator of LIN-12/Notch through genetic analysis in C. elegans; its ortholog, Fbw7, was subsequently found to be a tumor suppressor that contributes to T-cell acute lymphoblastic leukemia (T-ALL) via negative modulation of Notch1." (PMID 27646703, 2016). "For example, dIP, but not MACS, predicted MYC targeting by NOTCH1 in TALL cells; a regulatory interaction that is thought to play a key role in T cell acute lymphoblastic leukemia." (PMID 26040656, 2015).
T-cell acute lymphoblastic leukemia (continued). "However, unlike ICN1-3, ICN4 fails to induce T-cell acute lymphoblastic leukemia/lymphoma (T-ALL) and is unable to rescue the growth of Notch1-dependent T-ALL cell lines." (PMID 22022427, 2011).
acute lymphoblastic leukemia (167 papers, 2008 to 2025). Leukemia with an acute onset, characterized by the presence of lymphoblasts in the bone marrow and the peripheral blood. "RNA sequencing (RNA‐Seq) analysis of T‐cell acute lymphoblastic leukemia (T‐ALL) cells with mutations in Notch receptor 1 (NOTCH1) identified enhanced OXPHOS and glutaminolysis signatures." (PMID 38214418, 2024). "The resistance mechanisms in relapsed/refractory early T-cell progenitor acute lymphoblastic leukemia (ETP-ALL) carrying activating NOTCH1 mutations are unclear." (PMID 37612741, 2023). "The Group for Research in Adult Acute Lymphoblastic Leukemia (GRAALL) validated in adult T-ALL patients the clinical utility of a new oncogenetic classifier based on the mutational status of NOTCH1/FBXW7/PTEN/RAS (NFPR) genes." (PMID 33614543, 2020). "The MAb604.107 exhibited higher affinity for the “Gain-of-function” mutants of Notch1 NRR associated with T Acute lymphoblastic Leukemia (T-ALL)." (PMID 26046801, 2015). "It was further shown that human Tspan33 promotes γ-secretase cleavage of Notch and that depletion of Tspan33 might be a potential target in T-ALL, a rare yet aggressive form of lymphoblastic leukemia, which is associated with activating mutations of Notch1." (PMID 28066176, 2016). "Mechanistic details have started to emerge on how cyclin C acts as a tumor suppressor in T-cell acute lymphoblastic leukemia (T-ALL) Here, aberrant NOTCH1 expression is a causative factor in T-ALL development." (PMID 40358161, 2025). "The frequent identification of gain-of-function mutations in NOTCH1 in T-cell acute lymphoblastic leukemia/lymphoma (T-ALL) prompted the rapid development of the first clinical trial of Merck‘s GSI drug MK-0752 in patients with relapsed/refractory T-ALL." (PMID 38672496, 2024). "The oncogenic role of strong gain-of-function mutations in NOTCH1 has been experimentally demonstrated in T-cell acute lymphoblastic leukemia/lymphoma (T-ALL)." (PMID 38043798, 2024). "T-cell acute lymphoblastic leukemia (T-ALL) is a tumor resulting from the malignant transformation of T-cell progenitors via the mutations in the NOTCH1 gene." (PMID 38053150, 2023). "Notch1 mutation was first identified in patients with acute T-cell acute lymphoblastic leukemia (T-ALL) and occurs in approximately 50% of T-ALL." (PMID 36798826, 2023). "Expression restricted to BM compartment, upon BM transplantation in recipient mice, lead to aggressive T acute lymphoblastic leukemia (ALL) enriched with Notch1 mutations." (PMID 35158933, 2022). "NOTCH1 mutation is common in T-cell acute lymphoblastic leukemia (T-ALL), which is an aggressive hematologic malignancy." (PMID 36612059, 2022). "Accordingly, elevated Notch1 signaling is oncogenic in T cells driving acute lymphoblastic leukemia (T-ALL), whereas increased Notch2 signaling is associated with splenic MZB transformation." (PMID 33017398, 2020). "The activation of the pathway has been first described in T-cell acute lymphoblastic leukemia (T-ALL), where more than 50% of patients present hyperactivating mutation of Notch1 genes." (PMID 31817634, 2019). "T-cell acute lymphoblastic leukemia (T-ALL) represents approximately 15% of pediatric and 25% of adult ALL cases and is characterized by a high prevalence of activating mutations in the NOTCH1 gene." (PMID 30304769, 2018). "Aberrant Notch activation was first linked to cancer in 1991 when Notch1 was identified as part of a t(7:9)(q34;q34) translocation in patients with T-cell acute lymphoblastic leukemia (T-ALL)." (PMID 24959528, 2014). "Interestingly, altered Notch1 signaling alone in a T cell progenitor causes T cell acute lymphoblastic leukemia suggesting that Notch1 dysregulation may be a critical event for the CSC in this malignancy." (PMID 23805413, 2013).
acute lymphoblastic leukemia (continued). "Point mutations in the extracellular domain of NOTCH1 are one cause of T cell acute lymphoblastic leukemia (T-ALL); when patients with these mutations relapse after chemotherapy, they generally have mutations in FBW7." (PMID 20686701, 2010). "Notably, aberrant Notch1 signaling was originally associated with rare cases of T-cell acute lymphoblastic leukemia (T-ALL) in humans." (PMID 41294868, 2025). "Notch1 activation is present in many cancers (acute lymphoblastic leukemia, non-Hodgkin’s lymphoma, and prostate cancer, amongst others)." (PMID 40358161, 2025). "Our findings reveal a novel feedback loop regulation between NOTCH1 and USP11, underline the role of active deubiquitination in cancer, and provide a rationale for therapeutic targeting of USP11 in acute lymphoblastic leukemia." (PMID 38007584, 2024). "Furthermore, recent studies of T cell acute lymphoblastic leukemia (T-ALL) have revealed that an activating mutation in Notch1 commonly causes leukemia in cooperation with other oncogenic mutations." (PMID 36593298, 2023). "Notably, acute lymphoblastic leukemia (ALL) Notch1/FBXW7 mutated patients had a better response to the multiagent ALL BFM-95 protocol." (PMID 34680255, 2021). "The present study about glutamine dependence of Notch1‐driven lymphoblastic leukemia showed a connection between Notch1 signaling and glutamine metabolism." (PMID 33314742, 2021). "In acute lymphoblastic leukemia, NOTCH1 contributes to the upregulation of USP7 levels, and USP7, in turn, influences the stability of NOTCH1, which possibly forms a positive-feedback interaction between the two proteins." (PMID 34869041, 2021). "Moreover, GSIs were confirmed to have a therapeutic effect in T-cell acute lymphoblastic leukemia (T-ALL), where more than 50% of patients harbor NOTCH1 activating mutations." (PMID 34442029, 2021). "Activating NOTCH1 mutations are prevalent in hematological malignancies and sequenced in 40% to 70% of T cell acute lymphoblastic leukemia (T-ALL), in 10–15% of chronic lymphocytic leukemia (CLL) and mantle cell lymphoma (MCL) and a subset of diffuse large B cell lymphoma (DLBCL)." (PMID 33407740, 2021). "We assessed Notch pathway activity in a cohort of T cell acute lymphoblastic leukemia (T-ALL) patient samples, and found that the pathway activity score more accurately reflects Notch pathway activity than a prediction on the basis of NOTCH1 mutations alone." (PMID 33120947, 2020). "The NOTCH1-JMJD3-MLL complex was proved to enhance the cell growth-promoting effects of the NOTCH1 transcriptional program in acute lymphoblastic leukaemia of mice." (PMID 31701394, 2019). "Many aberrations in some signaling pathways are involved in ALLpathogenesis; amongst them, gain-of-function mutations in NOTCH1 genehave been described in more than 50% of T-cell acute lymphoblastic leukemia(T-ALL) cases, thus unraveling the role of Notch-mediated oncogenesis in lymphoidtissues." (PMID 29719609, 2018). "In acute lymphoblastic leukemia, Notch1 regulates cell proliferation and migration through CCR5 and CCR9, and in multiple myeloma Notch regulates CXCR4." (PMID 28137279, 2017). "For instance, Notch1 mutations occur in over 50% of both pediatric and adult T-cell acute lymphoblastic leukemia (T-ALL) cases, while Fbxw7 mutations are found in up to 20% of T-ALL cases." (PMID 28149836, 2016). "It is also notable that the clustering of MYB, NOTCH1, RUNX1, and FBXW7 mutations seen in this uncommon epithelial tumor ACC overlaps with frequent somatic mutations seen in human acute lymphocytic leukemia patients." (PMID 25587024, 2014). "Abnormal expression of Notch1 was first identified in human T lymphocytes in acute lymphoblastic leukemia." (PMID 23420695, 2013). "NOTCH1 is a major oncogenic driver in T cell acute lymphoblastic leukemia." (PMID 33909629, 2021).
acute lymphoblastic leukemia (continued). "We validate these findings in T cell acute lymphoblastic leukemia cell lines and patient samples and show that oncogenic NOTCH1 induces specific CTCF binding and they cooperatively activate expression of target genes, indicating transcriptional condensation phenomena." (PMID 32933554, 2020). "The functional effect of the different types of NOTCH1 mutations has been extensively studied in T-acute lymphoblastic leukemia (T-ALL), where most Notch1 alterations affect the heterodimerization domain of the receptor and lead to a constitutive ligand-independent Notch activation." (PMID 31616059, 2020). "Beginning with the first reports of an involvement of Notch1 in the development of 10% of T-cells acute lymphoblastic leukemias (T-ALL), investigations conducted in the last 20 years have shown Notch activation in the majority of solid tumors and hematological malignancies." (PMID 25629006, 2014). "miR-19, the cluster component with the highest expression in T-cell acute lymphoblastic leukemia (T-ALL) in a mouse model of Notch1-induced T-ALL, increases lymphocyte survival and induces leukemogenesis." (PMID 36672872, 2023). "For example, the epistatic activation of MYC, for instance, via NOTCH1 signaling in T-cell acute lymphoblastic leukemia (T-ALL) is essential to tumorigenesis (22, –24)." (PMID 36897988, 2023). "The first evidence linking Notch signaling to cancer was a chromosomal translocation targeting Notch1 in T-cell acute lymphoblastic leukemia (T-ALL)." (PMID 37255594, 2023). "The carcinogenic and pathogenic functions of NOTCH signaling in human cancer were demonstrated for the first time in T‐cell acute lymphoblastic leukemia (T‐ALL), with the identification of chromosomal rearrangement involving the NOTCH1 locus." (PMID 35900231, 2022). "The cellular receptor Notch1 is a central regulator of T‐cell development, and as a consequence, Notch1 pathway appears upregulated in > 65% of the cases of T‐cell acute lymphoblastic leukemia (T‐ALL)." (PMID 33314742, 2021). "RFX1 is also reported to interact with an intracellular active form of NOTCH-1 (ICN1) in human T-cell acute lymphoblastic leukemia (T-ALL) cells." (PMID 33964962, 2021). "Since Notch 1 is a key factor in T-cell development, it is clear that it has been well investigated in T-cell diseases such as acute lymphoblastic leukemia (T-ALL)." (PMID 33374160, 2020). "T cell acute lymphoblastic leukemia (T-ALL) is an immature hematopoietic malignancy driven mainly by oncogenic activation of NOTCH1 signaling." (PMID 29556394, 2018). "The T-cell 1acute lymphoblastic leukemia (T-ALL) is mainly driven by oncogenic activation of NOTCH1 signaling." (PMID 28561778, 2017). "Cooperation between miR-19 and Notch1 activation was also observed in T-cell acute lymphoblastic leukemia (T-ALL)." (PMID 26442266, 2015). "The first evidence of Notch’s involvement in tumorigenesis was noticed when a small subset of T cell acute lymphoblastic leukemia (T-ALL) was found to have constitutive activation of Notch signaling due to a chromosomal translocation of the mammalian NOTCH1 gene." (PMID 32630477, 2020). "In T cell acute lymphoblastic leukemia (T-ALL), a translocation on chromosome 9 results in the generation of a truncated form of Notch1, which lacks its N-terminal domain and results in expression of the constitutively active form (Notch1ICD) of the receptor leading to malignant conversion." (PMID 32784481, 2020). "Indeed, a common regulator of HSF1 and a series of key HSP genes was recently described for T cell acute lymphoblastic leukemia (T-ALL) in the intercellular-signaling receptor NOTCH1." (PMID 32331382, 2020). "The Notch1 pathway is frequently involved in human T cell acute lymphoblastic leukemia (T-ALL)." (PMID 29136506, 2017). "Moreover, ablation of cyclin D3 in mice bearing Notch1-driven T-cell acute lymphoblastic leukemia (T-ALL) triggers tumor cell apoptosis." (PMID 25914884, 2015).
acute lymphoblastic leukemia (continued). "Our aim was to understand the protein interaction network, using Notch1 protein name as query in STRING database and we generated a model to assess the significance of Notch1 associated proteins in Acute Lymphoblastic Leukemia (ALL)." (PMID 24688641, 2012). "Although depletion of DDX5 was reported to induce apoptosis by downregulating Notch1 signaling in lymphoblastic leukemia cells, Notch1 signaling was not suppressed by DDX5 depletion in prostate cancer cells." (PMID 27148684, 2016). "Here, we identified a regulatory feedback loop between NOTCH1 and the USP11 deubiquitinase in T-cell acute lymphoblastic leukemia (T-ALL)." (PMID 38007584, 2024). "The carcinogenicity of the pathway was first observed in human T-cell acute lymphoblastic leukemia (T-ALL), where, due to the release of N1ICD, NOTCH-1 was seen to be activated." (PMID 36359888, 2022). "Silencing Slfn2 prevents the growth of pre-leukemic T cells in T cell acute lymphoblastic leukemia (T-ALL), which is induced by the intracellular domain of NOTCH1 (ICN1) and attenuates the development and the progression of T-ALL in mice." (PMID 34571887, 2021). "In hematological malignancies, TRIB2 as a target gene of MEIS1, E2F1, and NOTCH1 participates in acute myeloid leukemia (AML) and T cell acute lymphoblastic leukemia (T-ALL)." (PMID 33794905, 2021). "Ikaros, a transcriptional regulator of hematopoietic differentiation, is deleted in acute lymphoblastic leukemia (ALL) and has previously been identified as a CIS in a screen conducted in transgenic mice expressing the Notch1 intracellular domain (NotchIC)." (PMID 18485879, 2008). "Retrovirus carrying a gain-of-function NOTCH1 mutant, the constitutively activated BCR-ABL1 kinase, or the fusion MLL-AF9 are used to induce T-cell acute lymphoblastic leukemia (T-ALL, chronic myeloid leukemia (CML), or acute myeloid leukemia (AML), respectively." (PMID 40589762, 2025). "It is uncertain that whether the treatment of proteasome inhibitors is also effective in NOTCH1 wild-type T-ALL, especially early T-cell precursor acute lymphoblastic leukemia (ETP-ALL) which confers a poor prognosis." (PMID 35004327, 2021). "In T acute lymphoblastic leukemia (T-ALL), an aggressive neoplasm of immature T-cells, Notch3 is commonly overexpressed but is not constitutively activated as Notch1 normally is." (PMID 33198378, 2020). "MYC-translocated T-lineage acute lymphoblastic leukemia (T-ALL) is a rare subgroup of T-ALL associated with CDKN2A/B deletions, PTEN inactivation, and absence of NOTCH1 or FBXW7 mutations." (PMID 30304769, 2018).